HMGA2 (high mobility group AT-hook 2)
Diseases named in the same sentence as HMGA2 in open-access papers (continued):
Sharing a sentence is not in itself a finding about the gene and the disease.
cancer (continued). "Recently, some studies have shown that HMGA2 expression was closely related to the progression, invasion, metastasis and prognosis of a number of malignant tumors, and tumors with high HMGA2expression were highly malignant, and prone to invasive metastasis and poor prognosis." (PMID 22613496, 2012). "In conclusion, HMGA2 silencing in RB cancer cells resulted in the deregulation of genes responsible for apoptotic, cell cycle, and cell adhesion mechanisms, thereby explaining the mechanisms by which cancer cell progression is suppressed in HMGA2-silenced RB cells." (PMID 23077401, 2012). "HMGA2 has complex functions, and the current study focuses on its relationship with cancer." (PMID 22613496, 2012). "Thus, Snail-mediated modulation of ECM proteins serves as one of the mechanisms by which cancer progression is controlled by HMGA2 silencing." (PMID 23077401, 2012). "Furthermore, it turns out that the balance between let-7 and HMGA2 governs the exit of cells from the undifferentiated and self-renewing state, and HMGA2 is now thought to be central in cancer in general." (PMID 20576167, 2010). "Consistent with our finding that the 293T spheres have markedly reduced Let-7 expression and increased H-ras and HMGA2, two known let-7 targets these authors showed that cancer stem cell population have markedly reduced let-7 and increased H-ras and HMGA2 expression." (PMID 20615238, 2010). "Furthermore, over-expression of both HMGA2 forms was associated with a strong repression of the epithelial marker CD24, consistent with the reported low level of CD24 in cancer stem cells." (PMID 20576167, 2010). "Importantly, our data demonstrate let-7-dependent deadenylation of the cancer-related HMGA2 mRNA during a physiologically relevant cellular differentiation process as well as in the experimental conditions employed for our R-luc reporter studies." (PMID 19710908, 2009). "However, only a few data on the expression of HMGA2 in malignant tumour originating from epithelial tissue are available." (PMID 14647145, 2003). "In HMGA2 immunohistochemical analysis, while only a small proportion of duct epithelial cells in the non-neoplastic tissue specimens showed HMGA2 immunoreactivity, a significantly higher proportion of carcinoma cells showed intense staining." (PMID 14647145, 2003). "Therefore, HMGA2 suppression could be an important therapeutic target as it reduces cancer cell proliferation, invasion, and migration." (PMID 40686703, 2025). "However, anti-aging therapies may introduce new challenges, particularly by maintaining elevated levels of HMGA2, which could indirectly promote cancer development." (PMID 39507236, 2024). "Notably, HMGA2 expression was regulated by miRNA and lncRNA in many cancers." (PMID 38910243, 2024). "Furthermore, HMGA2 has been implicated in maintaining the phosphorylation of ATR and CHK1, potentially switching the cell state from apoptosis to DNA repair, thereby promoting cancer cell survival and resistance to chemotherapy." (PMID 39085703, 2024). "According to available evidence, HMGA2 suppression may be a promising target for cancer therapy." (PMID 38361784, 2024). "Moreover, HMGA2 silencing corresponded with an increase in telomere aggregates, anaphase chromatin bridges, micronuclei formation and signs of telomere dysfunction, which culminated in chromosome segregation defects and increases in aneuploidy in cancer cells." (PMID 36980621, 2023). "Therefore, targeted regulation of HMGA2 expression may be a promising approach for future cancer treatments." (PMID 38304037, 2023). "HMGA2 was found to be a cancer promoter, and silencing HMGA2 could constrain GC progression." (PMID 37529164, 2023). "Thus, we cannot exclude that, in other cell types and in particular in cancer cells, Hmga2 could contribute to transcription regulation through the association with specific chromatin regions." (PMID 35918713, 2022).
cancer (continued). "In addition, HMGA2 maintains the cancer stem cell phenotype and chemoresistance in breast cancer." (PMID 34115920, 2021). "In addition, HMGA2 knockdown decreased cancer stem cell (CSC) features." (PMID 34680349, 2021). "The reduction in let-7 miRNAs represents one of the main mechanisms responsible for HMGA2 overexpression in atypical teratoid/rhabdoid tumors; therefore, the reconstitution of let-7 miRNA levels or HMGA2 knockdown may represent good therapeutic strategies for cancer treatment." (PMID 34439740, 2021). "However, some HMGA2-high cancers have normal levels of let-7." (PMID 32979259, 2020). "Therefore, HMGA2 is an attractive target for cancer therapy." (PMID 32842685, 2020). "Therefore, HMGA2 often functions as an oncogene to involve in the regulation of cancer progression." (PMID 32425695, 2020). "Thus, HMGA2 may be a useful marker for cancer diagnosis and treatment, as well as elucidating the biological behavior and prognosis of tumors." (PMID 32432318, 2020). "Thus, HMGA2 is an attractive target for many types of cancers." (PMID 31684108, 2019). "In addition, 5-FU is often used for the treatment of other cancer types; thus, further studies will determine whether suppression of HMGA2 could inhibit drug resistance to 5-FU in other tumors." (PMID 29515783, 2018). "All these studies reported that HMGA2 may be a promising prognostic factor for cancer patients." (PMID 29416690, 2018). "However, very few studies have investigated Hmga2 function in autochthonous cancer models in vivo." (PMID 30228296, 2018). "Importantly, HMGA2 depletion promoted the occurrence of novel cancer cell subpopulations with higher telomere numbers, suggesting the evolution of new HMGA2low genomic phenotypes fueled by telomere dysfunction with end-to-end telomere fusions followed by repeated BFB cycles." (PMID 26799419, 2016). "Thus, HMGA2 is a potential therapeutic target in cancer therapy." (PMID 26893968, 2016). "Thus, HMGA2 silencing was hypothesized to increase the sensitivity to anticancer drugs in cancer cells." (PMID 26893968, 2016). "Therefore, the detection of HMGA2 specific mRNA in peripheral blood may indicate the presence of cancer cells." (PMID 25749380, 2015). "Moreover, a recent study has shown that Hmga2 could promote cancer progression by acting as a competing endogeneous RNA (ceRNA) for let-7, adding another complexity to the mechanism by which Hmga2 can contribute to tumorigenesis." (PMID 25364713, 2014). "Loss of METTL1 reduces mature let-7e levels by 60%, upregulating the oncogenic target High Mobility Group AT-Hook 2 (HMGA2) and promoting cancer cell migration." (PMID 40809384, 2025). "CCNA2, SFN, HMGA2, SOX2, and RBP2 have been identified as significant biomarkers for cancer diagnosis and prognosis, particularly in liver cancer." (PMID 40251374, 2025). "For instance, Let‐7 family members have been reported to modulate oncogenes like RAS, HMGA2, and MYC in other cancer contexts, raising the possibility of unintended gene regulation in HCC." (PMID 40530890, 2025). "WHSC1 has been demonstrated to be an oncogenic factor and transcriptional target of HMGA2, and both HMGA2 and WHSC1 regulate the proliferation of cancer cells." (PMID 40896696, 2025). "Indeed, a significant correlation has been established between high HMGA2 expression and reduced overall survival in patients with diverse cancer types, including breast, lung, colorectal, prostate, gastric, liver, thyroid, bladder, pancreatic and ovarian cancers." (PMID 39085703, 2024). "The functions of HMGA2, such as DNA repair and the promotion of EMT, can be exploited by cancer cells." (PMID 38493165, 2024). "More importantly, we discuss extensively the mechanism through which HMGA2 regulates the EMT process and invasion in most cancers, including signaling pathways and the interacting RNA signaling axis." (PMID 38361784, 2024). "Therefore, HMGA2 may be essential in regulating the EMT process in cancer." (PMID 38361784, 2024).
cancer (continued). "In summary, our results revealed a regulatory mechanism by which HMGA2 coordinates GPX4 expression and underscores the potential value of targeting HMGA2 in cancer treatment." (PMID 38493165, 2024). "We chose 9 genes that were downregulated in LINC02159-knockdown NSCLC cells, including HMGA2, LIN28B, and YAP1, among others, as these genes have been demonstrated to be essential for cancer development and progression." (PMID 37537569, 2023). "The mRNA expression level of FXYD3, LGALS4, USH1C, ECI2, TGM2, and HMGA2 genes which are involved in EMT, drug resistance, and cancer progression were measured in HCT116/OX-R4.3 and HCT116/OX-R10 cells by qRT-PCR." (PMID 37535601, 2023). "let-7, the first miRNA discovered in humans, involves in many cancer-related genes such as c-MYC, HMGA2, and CCND1." (PMID 37689710, 2023). "HMGA2 not only binds ATM, but is an ATM substrate upon DNA damage, suggesting that HMGA2 functions in DSB signaling and repair upon genotoxic stress in cancer cells." (PMID 36980621, 2023). "In this regard, HMGA2 was shown to physically interact with PARP1, which stimulates PARP1 enzymatic activity on alkylated DNA from cancer cells treated with MMS." (PMID 36980621, 2023). "In conclusion, we found that VGLL3 promotes E‐cadherin repression and cell motility via HMGA2 in TGF‐β‐stimulated and mesenchymal cancer cells." (PMID 35366053, 2022). "Of these common target genes of miR-495-3p and miR-543, NRAS, HMGA2, and EGLN1 present in KEGG cancer metabolic pathways stand out (p-value < 0.05)." (PMID 35645340, 2022). "Consistent with these metrics, overexpression of HMGA2 in HK1 cell-derived exosomes promoted the passage of fluorescent probes, and cancer cells invaded the endothelial cell monolayer." (PMID 35388172, 2022). "HMGA2 is also an important factor in mediating TGF-β–induced EMT, a key event in cancer pathogenesis, and is upregulated by TGF-β/SMAD signaling." (PMID 36568239, 2022). "Except for HMGA2, IGF2BP2 markedly promotes functions of IGF and proliferation of cancer cells by binding and stabilizing HMGA1." (PMID 33568150, 2021). "As HMGA2 has been known to modulate DNA damage checkpoint proteins in cancer cells, we examined the expression and phosphorylation of ATM-CHK2 and ATR-CHK1 upon acute DNA damage in HMGA2-knockdown RB cells." (PMID 34887387, 2021). "In contrast to the oncogenic function of miR-150-5p in NSCLC cells, miR-150-5p was significantly downregulated in cancer stem cells in NSCLC, and the expression of miR-150-5p was demonstrated to inhibit the HMGA2 and β-catenin signaling pathways." (PMID 34944699, 2021). "Let-7d directly targets c-Myc, HMGA2, CCL7, PBX3 and COL3A1, and so inhibits thereby inhibiting cancer cell invasion and metastasis." (PMID 33507713, 2021). "Based on previous reports, HMGA2 plays a role in epithelial–mesenchymal transition (EMT) and is over-expressed in several cancers and is responsible for the invasive and metastatic behaviors of cancer cells." (PMID 33849540, 2021). "To detail the role of HMGA2 in TNBC development and progression, we studied its effect on core cancer phenotypes." (PMID 34680349, 2021). "In particular, HMGA2, LIN28B, and IGF2BP1 have been referred to as an “oncogenic triangle” that is critical for cancer initiation and that was also co-ordinately overrepresented in our data." (PMID 34706236, 2021). "Another dysregulated protein in our data, high mobility group AT-hook 2 (HMGA2), promotes ATM expression and promotes cancer cell resistance to genotoxic agents." (PMID 33251127, 2020). "On the contrary, let-7 has target genes [HMGA2 (High Mobility Group AT-Hook 2), IMP-1 (IGF2 mRNA-binding protein 1), LIN28B (Lin-28 homolog B), Ras, and MYC) important for cancer cell stemness." (PMID 32150871, 2020). "As supported by this view, our recent TCGA analyses have demonstrated that both HMGA2 and TERT expression levels were raised in the alterations of the TGF-β pathway genes in 33 cancer types." (PMID 32577156, 2020).
cancer (continued). "Subsequently, the downregulation of miR-145 leads to higher expression of cancer stemness regulatory genes Krüppel-like factor 4 (KLF4) and high-mobility group AT-hook 2 (HMGA2) and thus chemoresistance." (PMID 32756406, 2020). "Although HMGA1P6, HMGA1, and HMGA2 were all overexpressed in HGSOC, only HMGA1P6 and HMGA237 correlated with poor prognosis in cancer patients." (PMID 32127525, 2020). "In these cancers, the 3′-UTR of the mature HMGA2 mRNA transcript is truncated, allowing HMGA2 to avoid let-7-mediated downregulation." (PMID 32979259, 2020). "In this study, we have identified a novel role of HMGA2 in enhancing DNA damage‐induced PARP1 activity and diminishing the sensitivity of cancer cells to the PARP inhibitor olaparib." (PMID 30289618, 2019). "LIN28 inhibits Let-7 miRNA maturation to promote the expression of Let-7 targets HMGA2, KRAS, MYC22, and HRAS in cancer cells." (PMID 31712708, 2019). "Consistent with their convergent roles in the same pathway, low expression of HMGA2/RPSAP52 in differentiated cells and reexpression in cancer mirrors LIN28 levels, which is one of the key players in maintenance of the pluripotent state." (PMID 31484926, 2019). "Increased activity of let-7 allows negative regulation of cancer factors such as RAS, MYC, HMGA1, and HMGA2; in other words, the origin and maintenance of CSCs are impeded." (PMID 29853899, 2018). "Further support to the connected action of EZH2 and HMGA proteins derives from studies on other cancers in which EZH2 and HMGA (frequently HMGA2) converge towards the oncogenic achievement." (PMID 29853899, 2018). "EZH2 is an oncogene that is upregulated in human epithelial-type cancers such as NSCLC and whose expression is inhibited by let-7/miR-98 family members, along with that of c-Myc, high mobility group AT-hook 2, and LIN28." (PMID 28587210, 2017). "Lin-28B overexpression increased the expression of the HMGA2, c-MYC and KRAS genes, which are targeted by the cancer suppressor miRNA let-7." (PMID 28947981, 2017). "In accordance with our results, both HMGA2 and SLUG overexpression have been reported to promote and contribute to cancer progression." (PMID 29383160, 2017). "Using co-immunofluorescence imaging, we identified co-localizing foci of HMGA2 and TRF2 in interphase nuclei of cancer cells." (PMID 26799419, 2016). "HMGA2 silencing and the corresponding increase in TIF coincided with slower proliferation of cancer cells." (PMID 26799419, 2016). "Silencing of endogenous HMGA2 alone was sufficient to increase telomere dysfunction–induced foci (TIF) and the formation of micronuclei and anaphase bridges in cancer cells, indicating a protective function of HMGA2 in telomere stability." (PMID 26799419, 2016). "HMGA2 has been demonstrated to promote EMT by inducing the expression of Slug and Snail and then inhibiting the expression of E-cadherin in many cancer types." (PMID 26123544, 2015). "Others have also reported that HMGA2 expression is predictive of aggressive disease and poor outcomes in CRC, as similarly found in other cancers." (PMID 26244988, 2015). "Previous studies have revealed that HMGA2, SALL4 and Twist1 are involved in cancer stem cell self-renewal in different cell types." (PMID 25919570, 2015). "HMGA2 is a new member of the BER protein complex and interacts with human AP endonuclease 1 (APE1) to promote chemoresistance in cancer cells, including human undifferentiated thyroid cancer cells." (PMID 24723911, 2014). "The let-7 miRNA family, which was the first reported group of TSmiRNAs in cancer, represses a number of oncogenic proteins such as KRAS, high mobility group AT-hook 2 (HMGA2), and v-myc myelocytomatosis viral oncogene homolog (MYC)." (PMID 24551595, 2014). "It was previously shown that members of this family simultaneously inhibit multiple oncogenic pathways in cancer cells regulating the expression of relevant oncogenes like cmyc, ras, CDC25A, and HMGA2 among others." (PMID 23798998, 2013).
cancer (continued). "Most normal cell types that often develop HMGA2 positive cancers were largely HMGA2 negative at the selected experimental conditions." (PMID 40518465, 2025). "When overexpressed, HMGA2 stimulates biological pathways related to the cell cycle, apoptosis, angiogenesis, and Epithelial-Mesenchymal Transformation (EMT), which support cancer cell survival and proliferation, leading to cancer progression, increased aggressiveness, and poor prognosis." (PMID 40853523, 2025). "Unlike the Fox Chase Cancer Center tissues and the Kenyan patients, the Tissue Array samples showed a higher number of red signals (truncated HMGA2) than blue signals (wild-type HMGA2) in the Asian group." (PMID 41516076, 2025). "Moreover, HMGA2 interacts with poly(ADP-ribose) polymerase 1 (PARP1) by enhancing PARP1 activity and reducing cancer cell sensitivity to olaparib (a PARP inhibitor)." (PMID 40475780, 2025). "Whereas we found Ser100 and Ser104 phosphorylation in the Hmga2 C-terminal very low at 3 and 6 mo, Ser104 was elevated in cancer versus noncancer tissues." (PMID 38672675, 2024). "Understanding the mechanisms by which HMGA2 modulates CSC properties may provide novel therapeutic strategies for targeting CSCs and improving cancer treatment outcomes." (PMID 39085703, 2024). "In addition, the small nucleolar RNA host gene 16/let-7b-5p/HMGA2 (SNHG16/let-7b-5p/HMGA2) axis and the lncRNA LINC00355/miR-424-5p/HMGA2 axis play an important role in the EMT of cancers." (PMID 38361784, 2024). "We found that cancer cells with high levels of HMGA2 became less sensitive to enzalutamide but not to another drug, alisertib." (PMID 39123360, 2024). "Cancer development, differentiation, and progression are all suppressed by let-7's ability to inhibit oncogenic proteins such as RAS, HMGA2, c-Myc, and cyclin-D2." (PMID 38836981, 2024). "Similarly, the HMGA2-WHSC1 axis regulates cancer cell growth, proliferation, and metastasis, where WHSC1 acts as a transcription factor for oncogene HMGA2." (PMID 38725484, 2024). "Moreover, the high mobility group protein A2 (HMGA2) plays an interesting role, as HMGA2 competes with TGF-β type III receptors for the let-7 miRNA family, thus driving EMT in inducing cancer metastasis at the pulmonary level." (PMID 37190223, 2023). "Importantly, the increased expression of HMGA2 is relative to accelerating angiogenesis, strengthening EMT, invasion, and metastasis in cancer progression." (PMID 37689710, 2023). "Although HMGA2 is known as a critical transcriptional factor regulating EMT in cancers, its role in RPE cells undergoing EMT has not been elucidated thus far." (PMID 36945110, 2023). "Through its combined AP/dRP lyase activity and its PARP1-promoting function, HMGA2 supports cellular capacity for BER and single-stranded (ss) DNA repair, which are both particularly important in cancer cells undergoing oxidative DNA damage or those exposed to alkylating drugs." (PMID 36980621, 2023). "Emerging evidence has suggested the role of HMGA2 in TAM recruitment and polarization in cancer." (PMID 34976223, 2022). "Finally, RT-PCR and WB showed that CDH17, IGF2BP1, IGFBP1, ABCC2, and HMGA2 were differently expressed between human lung fibroblast (HLF) cells and cancer cells." (PMID 35903696, 2022). "High-mobility group AT-hook 1 (HMGA1) and high-mobility group AT-hook 2 (HMGA2), a non-histone protein, are overexpressed in diverse cancers, where they regulate developmental genes." (PMID 35328637, 2022). "The high-mobility group (HMG) is a class of small non-histone proteins abundant in the nucleus, among which HMGA2 is highly expressed in malignant tumors." (PMID 35400282, 2022). "Notably, among the genes downregulated upon DSCAM-AS1 knockdown were several proliferation activators of endometrial (and other) cancer cells, like NOTCH1, HMGA2, PTK2/FAK, FOSL1, GREM1 and EGR1." (PMID 35885035, 2022).